CPEB4 (cytoplasmic polyadenylation element binding protein 4)
Diseases named in the same sentence as CPEB4 in open-access papers (continued):
Sharing a sentence is not in itself a finding about the gene and the disease.
tumor (continued). "Therefore, the RNA immunoprecipitation analyses performed here provide a rich resource on CPEB4 controlled signalling cascades that could be explored as a platform for future comparative analyses across tumour types and cellular lineages." (PMID 27857118, 2016). "Therefore, the extent to which CPEBs may substitute for or cooperate with CPEB4 in other tumour types deserves further attention." (PMID 27857118, 2016). "To verify the effect of CPEB4 on the expression of CTNNB1 in vivo, we employed a nude mouse xenograft tumor model." (PMID 40084246, 2025). "The findings revealed significantly lower CPEB4 expression in HNSCC tissues compared to paraneoplastic tissues, prompting further investigation into its potential tumor-suppressive role." (PMID 40084246, 2025). "CPEB4 is overexpressed in inflammatory cells in patients with IBD and in CRC, favoring tumor development." (PMID 39408697, 2024). "According to literature, CPEB1 and CPEB3 act as tumor suppressors, while CPEB2 rather displays oncogenic features; in contrast, CPEB4 remains to be classified into one of these two categories." (PMID 34912244, 2021). "CPEB4 is aberrantly expressed in CRC tissues and correlates with tumor progression and poor overall survival in CRC patients." (PMID 31440515, 2019). "These mRNAs were expressed in a battery of normal (HPDE) and tumour (RWP-1, PANC-1 and MIA PaCa-2) pancreatic cells expressing variable levels of CPEB1 and CPEB4." (PMID 28300077, 2017). "On the other hand, CPEB4, analogous to CPEB1, was highly expressed only in a few tumors, with tumor cells often showing strong immunoreactivity in cell processes." (PMID 27256982, 2016). "After 5 weeks, we found that the tumor volume and mean tumor weight were significantly higher in the CPEB4 knockdown group than in the negative control group." (PMID 34976999, 2021). "Therefore, high levels of CPEB4 seem to be required for the oncoselective behaviour of the engineered virus and to prevent the CPE-mediated translational repression observed in non-tumour cells." (PMID 28300077, 2017). "One limitation of this study is the lack of experimental validation to confirm whether CPEB4 is secreted by other cells in the microenvironment and influences tumor cells." (PMID 40084246, 2025). "Thus, depletion of CPEB4 attenuates viral activity in tumour cells, while its overexpression in non-transformed cells increases viral replication." (PMID 28300077, 2017). "For CPEB2 and CPEB4 no methylation was detected in any of the investigated tumor specimens." (PMID 27256982, 2016). "Because we observed no growth defect or spontaneous tumor formation in CPEB4-KO mice, altered CPEB4 expression may affect proliferation of transformed cells but not normal cells." (PMID 27158894, 2016). "CPEB4 has been reported to exhibit dual roles in tumors, with its protein levels significantly upregulated in early-stage HCC but reduced in late-stage HCC, as observed in paired tumor and adjacent non-tumor liver specimens from 49 HCC patients." (PMID 40084246, 2025).
genetic diseases (1 paper, 2024). "However, concrete evidence linking CPEB4 variants to KS/IHH or other genetic diseases is currently lacking." (PMID 38628584, 2024).
CPEB4 also shares sentences with these, for which no sentence is quoted: gastric cancer (3 papers); Huntington disease (2); Anxiety (1); Atrophy (1); autism spectrum disorder (1); autoimmune disease (1); brain glioma (1); Cerebral ischemia (1); cervical carcinoma (1); diabetes (1); Down syndrome (1); Fibroadenoma (1); gallbladder cancer (1); Greig cephalopolysyndactyly syndrome (1); Hyperglycemia (1); infection (1); Kallmann syndrome (1); kidney cancer (1); metastatic tumors (1); microcephaly (1); nasopharyngeal carcinoma (1); neurological disorder (1); oral cancer (1); pancreatic adenocarcinoma (1); Pitt-Hopkins syndrome (1); renal carcinoma (1); renal clear cell carcinoma (1); respiratory diseases (1); schizophrenia (1); skin cancer (1).